TRPM7 (transient receptor potential cation channel subfamily M member 7)
Diseases named in the same sentence as TRPM7 in open-access papers (continued):
Sharing a sentence is not in itself a finding about the gene and the disease.
Obesity (continued). "Our findings showed that TRPM7 strongly stimulated NF-κB signaling in adipocytes, suggesting that TRPM7 may constitute an essential promoter in a positive feedback loop to fine-tune inflammatory responses in adipocytes, thereby contributing to chronic and low-grade metabolic inflammation in obesity." (PMID 36717580, 2023). "Therefore, the roles of TRPM7 and TRPV2 in the regulation of adipocyte differentiation and obesity might involve a cellular distention mechanism." (PMID 33195411, 2020). "Thus, the processes of releasing intracellular Ca2+ or the subsequent SOCE, which may occur concomitantly with TRPM7 channel activity, are not considered salient triggers of the NF-κB cascade and adipose tissue inflammation in obesity." (PMID 36717580, 2023). "Serum TNF-α, IL6, IL1β and MCP-1 levels have been identified upregulated in obese mice and modulated by adipocyte TRPM7 knockout in our study, indicating that adipocyte TRPM7 might be regulated by aberrant cytokines with coupled positive-plus-negative feedback circuits in response to obesity." (PMID 36717580, 2023).
amyotrophic lateral sclerosis (6 papers, 2014 to 2024). Amyotrophic lateral sclerosis (ALS) is a neurodegenerative disease characterized by progressive muscular paralysis reflecting degeneration of motor neurons in the primary motor cortex, corticospinal tracts, brainstem and spinal cord. "A variant of TRPM7 with a missense mutation (T1482I) is found in a subset of patients with Guamanian amyotrophic lateral sclerosis (ALS-G) and parkinsonism dementia (PD-G)." (PMID 24952306, 2014). "Loss of function mutations in TRPM7 and TRPM2 have been associated with Western Pacific Amyotrophic Lateral Sclerosis (ALS) and Parkinsonism Dementia (PD)." (PMID 33853504, 2021). "Overexpression of TRPM7 has been reported to increase H2O2-mediated injury, suggesting that TRPM7 is a potential target for neurodegenerative diseases.In addition, scarcity of Ca2+ and Mg2+is responsible for guamanian amyotrophic lateral sclerosis (ALS-G) and parkinsonism dementia (PD-G)." (PMID 32643506, 2020).
epilepsy (6 papers, 2010 to 2023). A brain disorder characterized by episodes of abnormally increased neuronal discharge resulting in transient episodes of sensory or motor neurological dysfunction, or psychic dysfunction. "Within the brain, TRPM7 is activated and expressed during epilepsy, perpetuating a positive feedback loop and contributing to the production of ROS." (PMID 36902145, 2023). "Other TRPM channels that have the potential to be therapeutic targets in epilepsy include TRPM7, where inhibition reduced the seizure-induced expression of TRPM7 channels and reduced ROS-related neuronal death." (PMID 36902145, 2023). "Carvacrol, a naturally occurring monoterpenic phenol that (among other mechanisms) inhibits TRPM7, was active in the perforant path stimulation kindling model of epilepsy, and inhibited recurrent status epilepticus." (PMID 35805072, 2022). "Researchers found that carvacrol, a natural inhibitor of TRPM7 channel, suppressed the recurrent epilepticus, early seizures, and hippocampal cell death, indicating the detrimental function of TRPM7 in mediating epilepsy." (PMID 32643506, 2020). "Considering the significant role of ions such as Ca2+, Mg2+ and Zn2+ in triggering epilepsy, the involvement of TRPM7 in epilepsy has also been discussed." (PMID 32643506, 2020). "Importantly, conditions associated with low serum magnesium levels can lead to seizures, thus possibly linking the TRPM7 channel with epilepsy." (PMID 37328275, 2023). "Despite this, the role of TRPM7 channels in seizures and/or epilepsy is still unclear." (PMID 37328275, 2023). "Moreover, TRPM7 has been shown to be activated during epilepsy." (PMID 33748103, 2021). "Three TRPM channels that have shown direct effects in epilepsy include TRPM2, TRPM3, and TRPM7." (PMID 36902145, 2023). "TRPC1, TRPC3-7, TRPM2, TRPM7, TRPV1, TRPV4, and TRPA1 have been shown to be involved in epilepsy." (PMID 33748103, 2021).
head and neck cancer (6 papers, 2013 to 2023). A primary or metastatic malignant neoplasm affecting the head and neck. "Studies have shown that the activation of TRPM7 channel is very important for human head and neck cancer cells." (PMID 38156103, 2023). "Activation of TRPM7 channel is very important for human head and neck cancer cells." (PMID 38156103, 2023). "After analyzing the overexpression of TRPM7, NFATC3, and Notch1 within different head and neck cancer cell lines, we screened cell lines suitable for subsequent experiments." (PMID 35771152, 2022).
Hyperglycemia (6 papers, 2013 to 2024). An increased concentration of glucose in the blood. "Accordingly, high-fat–fed mice with a genetic loss of TRPM7 kinase activity displayed a marked glucose intolerance accompanied by hyperglycemia." (PMID 36574297, 2023). "In a hyperglycemia mouse model, increased levels of Trpm7, INOS, Grp78 and Chop mRNAs were observed and associated to ER stress and apoptosis cascade activation." (PMID 36613628, 2022). "TRPM7 activity or expression would increase in neurons, vascular cells, and monocytes under the state of hyperglycemia." (PMID 38308007, 2024). "TRPM7 channels modulate the expression of caspase-12 and CHOP, and their overexpression/upregulation is associated with hyperglycemia-induced ER stress and resultant neuronal cell damage." (PMID 36613628, 2022). "This study investigated the change of transient receptor potential melastatin 7 (TRPM7) expression by high glucose and its role in hyperglycemia induced injury of vascular endothelial cells." (PMID 24223965, 2013). "Reactive oxygen species (ROS)-TRPM7-ERK1/2 axis plays an important role in hyperglycemia-induced development of the proliferative phenotype in rat aortic vascular smooth muscle cells, where TRPM7 knockdown partially blocked the high glucose-induced phenotype switching." (PMID 38308007, 2024). "In combination of this finding and ours, we speculate that increased ROS production and oxidative stress in hyperglycemia conditions might be responsible for the increased expression of TRPM7 in HUVECs." (PMID 24223965, 2013). "Thus, the current study was designed to investigate 1) the effect of hyperglycemia on TRPM7 expression in HUVECs; and 2) the role of TRPM7 in hyperglycemia-mediated injury of HUVECs." (PMID 24223965, 2013). "In contrast, TRPM7 channel plays a negative function in human umbilical endothelial cells (HUVECs) including inhibition of proliferation and migration and enhancement of hyperglycemia-induced injury." (PMID 25799367, 2015). "Although TRPM7 channel has been known to play an important role in neuronal viability and response to cellular stress, there have been no studies focusing on its role in hyperglycemia induced vascular endothelial cell injury." (PMID 24223965, 2013).
leukemia (6 papers, 2018 to 2026). A malignant (clonal) hematologic disorder, involving hematopoietic stem cells and characterized by the presence of primitive or atypical myeloid or lymphoid cells in the bone marrow and the blood. "In previous studies, we employed a human leukemia HAP1 cell line (referred to as clone KO-04) carrying a frame-shift mutation in the TRPM7 gene." (PMID 39513908, 2024). "To circumvent the pitfalls imposed by the overexpression of recombinant TRPM7, we took advantage of human haploid leukemia (HAP1) cells that lack endogenous TRPM7 currents due to a frameshift mutation introduced in the TRPM7 locus." (PMID 30770447, 2019). "We recently demonstrated a direct phosphorylation of AKT and SMAD2 via the TRPM7 kinase, influencing downstream signaling in murine and human immune and leukemia cells, respectively." (PMID 41326173, 2026). "Transcriptome profiling of human leukemia HAP1 cells revealed that TRPM7 plays a regulatory role in the expression of several transcripts, including HER2 (ERBB2)." (PMID 39513908, 2024). "In the present study, we conducted transcriptome profiling of human leukemia HAP1 cells to get insights on cellular responses triggered by inhibition of the TRPM7 channel using the pharmacological agent NS8593." (PMID 39513908, 2024). "Here, we used genome-wide transcriptome profiling of human leukemia HAP1 cells to examine cellular responses caused by the application of NS8593, the potent inhibitor of the TRPM7 channel, in comparison with two independent knockout mutations in the TRPM7 gene introduced by the CRISPR/Cas9 approach." (PMID 39513908, 2024). "In the present study, we conducted transcriptome profiling of human leukemia HAP1 cells to characterize cellular responses after genetic inactivation and pharmacological inhibition of TRPM7." (PMID 39513908, 2024). "TRPM7 has been shown to play a pivotal role on differentiation of SH-SY5Y neuronal cell line and human erythromyeloid leukemia cell line K562, and its inhibition prevents differentiation of human lung fibroblasts." (PMID 35163580, 2022).
liver fibrosis (6 papers, 2019 to 2024). "Carvacrol inhibit the expression of TRPM7 and inhibit the proliferation and activation of HSCs to alleviate liver fibrosis by modulating MAPK signaling pathway." (PMID 39359922, 2024). "To conclude, the upregulation of TRPM7, TRPM8, TRPV3, TRPV4, and TRPC6 is significantly associated with the onset and progression of liver fibrosis." (PMID 37569884, 2023). "Previously, activation of TRPM7 only in hepatic stellate cells was thought to be responsible for liver fibrosis and elevation of serum aminotransferases in a mouse model of carbon tetracloride-induced fibrosis." (PMID 37299589, 2023). "Besides a role for TRPM7 in neurodegenerative diseases, TRPM7 is involved in fibrotic diseases, such as liver fibrosis, pulmonary fibrosis, and cardiovascular fibrosis." (PMID 30453391, 2019). "In the context of liver fibrosis, the upregulation of TRPC6, TRPV3, TRPV4, and TRPM7 channels promotes the activation of HSCs and the production and accumulation of ECM components, including α-SMA and COL1A1." (PMID 37569884, 2023). "Consequently, blocking TRPM7 to impede HSC activation and proliferation and induce apoptosis may represent a promising approach to prevent or reverse liver fibrosis." (PMID 37569884, 2023).
Myocardial fibrosis (6 papers, 2018 to 2025). "Nevertheless, extending these observations to animal models of myocardial fibrosis associated with HF or diabetes is strongly recommended to place TRPM7 among the novel molecular targets to treat fibrosis-associated cardiac disorders." (PMID 40149710, 2025). "Our previous studies have revealed that there is a positive feedback between TGF-β1 and TRPM7, both of which are involved in myocardial fibrosis." (PMID 37187923, 2023). "In the present study, TRPM7 expression was increased in SAN tissues in SSS rats together with a significant increase in Smad2 phosphorylation level, suggesting the involvement of TRPM7/Smad2 in Ang II-mediated myocardial fibrosis." (PMID 29511803, 2018). "Further study will be needed to determine if TRPM7 plays a regulatory role in other myocardial fibrosis signaling pathways." (PMID 29511803, 2018). "TRPM2, TRPM4 and TRPM7 emerged as the sole TRPM isoforms involved in myocardial fibrosis." (PMID 40149710, 2025). "Transient receptor potential melastatin 7 (TRPM7) mediated Ca2+ signaling is required for TGF-β induced myocardial fibrosis and could serve as a common pathway in the fibrotic cascade response." (PMID 40881586, 2025). "There are also findings suggesting that transient receptor potential melastatin 7 (TRPM7) mediated Ca2 + signaling is required for TGF-β induced myocardial fibrosis and could serve as a common pathway in the fibrotic cascade response." (PMID 40881586, 2025). "Moreover, there is positive feedback between TGF-β1 and TRPM7, both of which can promote the development of myocardial fibrosis." (PMID 37187923, 2023). "Also, many signaling pathways are involved in myocardial fibrosis, but we only studied the effect of TRPM7 on collagen synthesis in the myocardium through Ang II/Smad2 signaling." (PMID 29511803, 2018). "Thus, our findings suggest that the activation of TRPM7/Smad2 signaling by Ang II is an important mechanism leading to myocardial fibrosis in SAN tissues in SSS rats, indicating that TRPM7 is a potentially therapeutic target for SSS treatment." (PMID 29511803, 2018).
cardiac hypertrophy (5 papers, 2014 to 2021). "Mice with global TRPM7 deficiency, or TRPM7 kinase domain deletion (TRPM7+/Δkinase mice), were significantly more prone to cardiac hypertrophy, fibrosis, and inflammation." (PMID 33922466, 2021). "TRPM7-deficient mice exhibited cardiac hypertrophy and abnormal function assessed by echocardiography." (PMID 31250885, 2020). "TRPM7-deficient mice had significant cardiac hypertrophy, fibrosis, and inflammation." (PMID 31250885, 2020). "Interestingly, a recent study by Rios and colleagues reported that TRPM7-deficient mice with kinase domain deletion (TRPM7+/Δkinase) exhibit cardiac hypertrophy, fibrosis, and inflammation." (PMID 31547577, 2019). "TRPM7+/Δkinase mice had cardiac hypertrophy and increased fibrosis as evidenced by approximately three-fold increase in collagen content." (PMID 31250885, 2020). "Interestingly, two different phenotypes were developed in Trpm7-/-mice adulthood: one developing cardiac hypertrophy with heart blocks (50% penetrant), and the other with normal heart size and devoid of heart blocks." (PMID 25531103, 2014).
diabetes (5 papers, 2009 to 2024). "We analyzed 20 haplotype-tagging single nucleotide polymorphisms (SNPs) in TRPM6 and 5 common SNPs in TRPM7 for their association with diabetes risk." (PMID 19149903, 2009). "Neither was there any evidence of association between common TRPM6 and TRPM7 haplotypes and diabetes risk." (PMID 19149903, 2009). "Neither was there any evidence of association between common TRPM7 haplotypes and diabetes risk (P for global test = 0.43)." (PMID 19149903, 2009). "Of the 5 TRPM7 SNPs, rs3109881 and rs3098198 showed significant associations with diabetes risk (rs3109881, additive P = 0.04; and rs3098198, additive P = 0.03 and dominant P = 0.03)." (PMID 19149903, 2009). "Thus, it is important to further examine in human population data whether magnesium intake modifies any common genetic effects of TRPM6 and TRPM7 on diabetes risk." (PMID 19149903, 2009). "Targeting TRPM7 channels might be a novel therapeutic strategy for vascular complications in diabetes." (PMID 24223965, 2013). "According to the findings, in the DRGs of mice and rats with diabetes mellitus, injections of antioxidants such as selenium, melatonin, and Noopept reduced the oxidant, TRPM2, TRPM7, and TRPV1 stimulator effects of STZ." (PMID 38976129, 2024). "Suggests that the RIP3/MLKL/TRPM7 necroptotic pathway may affect penile tissue function mainly through local effects and does not improve diabetes." (PMID 39329120, 2024).
ischemic heart disease (5 papers, 2017 to 2023). "Our data also suggest that the density of the TRPM7 current in human atrial cardiomyocytes highly depends on the underlying pathology, being higher in cells from patients with AF, especially those with history of coronary artery disease." (PMID 28129376, 2017). "Importantly, attention has also been drawn to the involvement of TRPM7 in ischemic heart disease (IHD), since increased expression of TRPM7 and TRPM6 was observed in cardiac biopsies from patients with IHD." (PMID 36818331, 2023).
non-small cell lung carcinoma (5 papers, 2020 to 2024). A group of at least three distinct histological types of lung cancer, including non-small cell squamous cell carcinoma, adenocarcinoma, and large cell carcinoma. "It has been reported that TRPM7 relies on calcium signaling to enhance O-GlcNAcylation levels of c-Myc and Cav-1 in cells, inhibiting their degradation and promoting the movement and metastasis of non-small cell lung cancer (NSCLC) cells." (PMID 39633507, 2024). "In the non-small cell lung cancer (NSCLC) cell line A549, the TRPM7 channel is over-expressed after stimulation of epidermal growth factor (EGF), and an increased cell migration is observed." (PMID 36844925, 2022).
retinoblastoma (5 papers, 2013 to 2024). A malignant tumor that originates in the nuclear layer of the retina. "Another study demonstrated that TRPM7 is involved in the proliferation of retinoblastoma cells and in the progression of the G1/S cell division cycle by modulating spontaneous activated Ca2+-influx pathways." (PMID 32168794, 2020).
rheumatoid arthritis (5 papers, 2018 to 2024). A chronic, systemic autoimmune disorder characterized by inflammation in the synovial membranes and articular surfaces. "For example, expression of transient receptor potential cation channel subfamily M member 7 (TRPM7) is elevated in articular chondrocytes from adjuvant arthritis rats, human rheumatoid arthritis patients, and erastin-treated cultured chondrocytes." (PMID 38844964, 2024). "TRPM7 siRNA also increased the rheumatoid arthritis fibroblast-like synoviocytes apoptosis." (PMID 29615639, 2018). "According to research, TRP channels have become drug targets for the treatment of RA as there are multiple TRP channels in rheumatoid arthritis synovial fibroblasts, including TRPV1, TRPA1, TRPC5, TRPM3, TRPM7, and TRPM8." (PMID 30792744, 2019).
breast tumor (4 papers, 2013 to 2024). "A previous study by Mandavilli found high immunohistochemical staining for the TRPM7 channel in breast tumours with associated calcifications." (PMID 30679450, 2019). "ANXA1 binds to cell membrane phospholipids and can be phosphorylated by the epidermal growth factor receptor, TRPM7 channel kinase 1, protein kinase A and protein kinase C. Its expression has been linked to carcinogenesis and metastasis in various tumor types, including breast tumors." (PMID 39040439, 2024). "This hypothesis is supported by the significant number of histopathological studies demonstrating altered expression of mineralisation associated proteins including BMP2, osteopontin, RUNX2, and TRPM7 in breast tumours with associated microcalcifications." (PMID 30679450, 2019). "SKF96365, a drug that blocks several Ca2+ permeable channels including TRPM7 and CRAC/Orai1, reduced migration of a breast tumor cell line." (PMID 23620825, 2013). "The study shows that TRPM7 is overexpressed in breast tumor tissues when compared to the adjacent non-tumor ones." (PMID 24952306, 2014).